NAT2 (N-acetyltransferase 2)
Diseases named in the same sentence as NAT2 in open-access papers (continued):
Sharing a sentence is not in itself a finding about the gene and the disease.
lung carcinoma (8 papers, 2006 to 2025). "In Yakuts, the allele NAT2*7 (857A) and the genotype NAT2*7 (857 G/A) are markers of increased risk of lung cancer." (PMID 33092525, 2020). "Several studies have attempted to explain the association between NAT2 polymorphism and numerous cancer types including breast, lung cancer, acute lymphoblastic leukemia and acute myeloid leukemia." (PMID 33369472, 2020). "We used odds ratios (ORs) with corresponding 95% confidence intervals (CIs) to evaluate the susceptibility to lung cancer associated with NAT2 polymorphisms." (PMID 26656326, 2015). "In conclusion, our meta-analysis demonstrated that TT genotype in C282T polymorphism among 5 SNPs in NAT2 gene was a susceptibility factor for lung cancer." (PMID 26656326, 2015). "But increased risk of lung cancer was found in association with NAT2 C282T polymorphism (TT vs. CC + TC: OR = 1.58, 95% CI = 1.11–2.25)." (PMID 26656326, 2015). "In terms of phenotypes, we investigated the acetylator status of NAT2 polymorphisms associated with lung cancer risk." (PMID 26656326, 2015). "We obtained for the reference allele NAT2*4 [c.481C + c.590G + c.857G] in 22.3% and 24.6% for control and lung cancer patients, respectively." (PMID 16827944, 2006). "We found at least 15 case-control studies (five of which are published in 2005) on NAT2 variants and lung cancer risk in different ethnic groups and exposure variables, such as cigarette smoke and asbestos." (PMID 16827944, 2006). "Many studies have been undertaken on NAT2 variants and lung cancer risk, of which five recently published (see Background)." (PMID 16827944, 2006). "We researched 18 published studies, involving 4,016 patients and 5,469 controls, to more accurately assess the effects of NAT2 polymorphism on lung cancer risk and to investigate whether smoking is associated." (PMID 33777732, 2021). "Our meta-analysis demonstrates that TT genotype in NAT2 C282T polymorphism may be a risk factor for lung cancer susceptibility." (PMID 26656326, 2015). "So far, the role of NAT2 acetylator status in lung cancer risk is unclear." (PMID 26656326, 2015). "However, with the exception of two studies on Chinese populations, none of the 15 reviewed studies found an overall association of NAT2 acetylation genotypes to lung cancer risk." (PMID 16827944, 2006). "We did not only analyzed overall rapid or slow acetylator genotypes, but paid particular attention to individual NAT2 genotypes which may confer susceptibility to colon and lung cancer." (PMID 16827944, 2006). "Finally, lacking some original data of genotypes, the comprehensiveness and precision of association between NAT2 polymorphisms and lung cancer may be influenced." (PMID 26656326, 2015). "Thus, the relevance of the NAT2 polymorphisms to lung cancer risk is of particular importance." (PMID 26656326, 2015). "For instance, NAT2 genotypes may provide a risk to lung cancer when combined with other genes." (PMID 16827944, 2006). "To determine NAT2 genotypes in our colon and lung cancer patients and control population of healthy individuals, we investigated three sequence variations reported to result in impaired acetylation." (PMID 16827944, 2006). "We have also undertaken a systematic review of NAT2 studies on lung cancer and we incorporated our present results in a meta-analysis consisting of 16 studies, 3,865 patients and 6,077 control subjects." (PMID 16827944, 2006). "The role of NAT2 acetylation status in lung cancer is likewise unclear, in which both the rapid and slow acetylator genotypes have been associated with disease." (PMID 16827944, 2006). "Indeed, significant associations of NAT2 acetylation genotypes to lung cancer risk were obtained from non-smoking women Chinese women, and not on male smokers which were mainly the case subjects in several studies (for example, 7 studies with 76–100% males and 89–100% smokers in lung cancer cases)." (PMID 16827944, 2006).
lung carcinoma (continued). "So far, the role of NAT2 acetylation status in lung cancer is unclear, in which both the rapid and slow acetylator genotypes have been implicated in disease." (PMID 16827944, 2006). "Studies have shown that smoking, chronic lung disease, air pollution, occupational exposure factors, people with NAT2 nonrapid (slow intermediate) phenotype, and low education levels have a significantly increased risk of lung cancer." (PMID 35300346, 2022). "The results suggested that people with NAT2 non-rapid (slow + intermediate) phenotype have a significantly increased risk of lung cancer." (PMID 33777732, 2021). "In terms of genotypes, no obvious relationship was found between 5 SNPs in NAT2 gene and lung cancer susceptibility." (PMID 26656326, 2015). "In terms of genotypes, overall, no obvious relationship was observed between NAT2 polymorphisms and lung cancer risk." (PMID 26656326, 2015). "Since the effect of NAT2 on lung cancer may be influenced by ethnicity and smoking status, we carried out a stratified meta-analysis of studies based on Asians, Caucasians and, male Caucasian smokers." (PMID 16827944, 2006). "Closer examination, however, of the different studies on NAT2 acetylation status and lung cancer risk, showed lack of uniformity in the design, analysis, reporting and exposure variables (e.g. smoke, asbestos) tested." (PMID 16827944, 2006). "Most studies obtained no overall association of NAT2 acetylator genotypes to the development of lung cancer, but specific risks were detected." (PMID 16827944, 2006). "Meta-analysis of 16 NAT2 studies on lung cancer did not evidence an overall association of the rapid or slow acetylator status to lung cancer." (PMID 16827944, 2006). "Additionally, the acetylator status of NAT2 polymorphisms was not in association with lung cancer susceptibility." (PMID 26656326, 2015). "Indeed, even in a very big study subjects of 1,115 lung cancer cases, and in which age, gender, smoking status and pack years of smoking were considered, no overall relationship between NAT2 genotypes and lung cancer risk was obtained." (PMID 16827944, 2006). "Additionally, the acetylator status of 5 SNPs in NAT2 gene may not be associated with lung cancer risk." (PMID 26656326, 2015). "The combination NAT2 slow-CYP1A1 rapid acetylator were at highest risk for lung adenocarcinoma in non-smoking females or the NAT2-CYP1A1 rapid acetylators may also predispose higher risk to lung cancer in female never smokers." (PMID 16827944, 2006).
diabetes (7 papers, 2011 to 2025). "NAT2 has been proved to be a regulator of mitochondrial function and associated with metabolism-related diseases, such as diabetes." (PMID 41169617, 2025). "Together with the earlier reported NAT2 polymorphism these SNPs explain less than 5% of the SAF variance in the non-diabetes population." (PMID 36536295, 2022). "NAT2 has been reported associated with several diseases through its function of metabolism regulation, such as cancer, neurodegenerative diseases, and diabetes." (PMID 41169617, 2025). "However, other groups showed a relationship between different NAT2 genotypes NAT2∗6A, NAT2∗5A, NAT2∗14A, and NAT2∗7B and risk for diabetes mellitus." (PMID 32626768, 2020). "The association between different NAT2 genotypes and risk for diabetes mellitus is controversial." (PMID 32626768, 2020). "Replication of the association of NAT2 with G-H1 is needed in individuals with diabetes, as is a determination of the association in those without diabetes." (PMID 24934506, 2014). "We identified a robust association between NAT2 and SF in people with and without diabetes." (PMID 24934506, 2014). "Using a GWAS, we identified rs1495741 located 14 kb downstream of NAT2 to be associated with SF in individuals with type 1 diabetes, and the same signal (rs4921914, r2 = 1.0) was observed in a separate discovery cohort of individuals without diabetes." (PMID 24934506, 2014). "There was suggestion that a stronger effect of NAT2 on SF might exist in individuals with type 2 diabetes than in those without diabetes." (PMID 24934506, 2014).
systemic lupus erythematosus (6 papers, 2007 to 2025). An autoimmune multi-organ disease typically associated with vasculopathy and autoantibody production. "Diversity within NAT2 has been related to the developing drug side effects such as hepatotoxicity, peripheral neuropathy, lupus, and susceptibility to some kinds of cancer." (PMID 37023111, 2023). "With the aim being to achieve individual optimization of co-trimoxazole therapy in patients with systemic lupus erythematosus (SLE), we investigated genetic polymorphisms in the NAT2 gene (which encodes the metabolizing enzyme of sulphamethoxazole)." (PMID 17335581, 2007).
endometriosis (5 papers, 2018 to 2021). The growth of functional endometrial tissue in anatomic sites outside the uterine body. "In a subsequent study, this group also identified significant differences in the arylamine N-acetyltransferase 2 (NAT2) gene polymorphisms between disease-free women and patients with endometriosis." (PMID 35153815, 2021). "The relationship between endometriosis and polymorphisms in NAT2 gene was investigated in a UK population." (PMID 32626768, 2020). "Specifically, previous studies have evaluated the relationship between NAT2 polymorphisms and the risk of endometriosis; however, contradictory results have been obtained." (PMID 31881062, 2019). "We comprehensively evaluated NAT2 phenotypes with respect to the risk of endometriosis, including a subgroup analysis according to ethnic groups." (PMID 31881062, 2019). "In a subgroup analysis based on ethnicity, the NAT2 slow acetylation phenotype was found to increase the risk of endometriosis in Asians." (PMID 31881062, 2019). "We concluded that the NAT2 slow acetylation phenotype is a risk factor for endometriosis in the Asian population." (PMID 31881062, 2019). "Further large-scale case-control studies are needed, with specific designs to account for the disease stage, for a more in-depth and thorough exploration of the relationship between NAT2 polymorphisms and endometriosis." (PMID 31881062, 2019). "Based on a subgroup analysis based on ethnicity, the NAT2 slow acetylation phenotype was found to increase the risk of endometriosis in Asians." (PMID 31881062, 2019). "In this study, associations between NAT2 phenotypes as well as single nucleotide polymorphisms (SNPs) within NAT2 (i.e. rs1799929, rs1799930, rs1208, and rs1799931) and endometriosis risk were evaluated using a meta-analysis approach." (PMID 31881062, 2019). "ORs (odds ratios) and 95% CIs (95% confidence intervals) were used to estimate the associations between NAT2 polymorphisms and endometriosis risk." (PMID 31881062, 2019). "C481T, G590A, A803G and G857A polymorphisms in exon 2 of NAT2 with the risk of endometriosis were investigated in an Iranian population." (PMID 30090210, 2018). "The NAT2 481C, 803A, 590A, 587A haplotype was associated with a higher risk of endometriosis in Iranian population." (PMID 30090210, 2018). "NAT2 has been suggested as a susceptibility factor in endometriosis; however, the results of studies have been controversial." (PMID 30090210, 2018). "The results of a few studies that evaluated the association of NAT2 polymorphisms and acetylator phenotypes with the endometriosis are controversial 19–23." (PMID 30090210, 2018). "This is an association study and totally 141 women with diagnosis of endometriosis and 158 healthy women as control group were analyzed for NAT2 gene polymorphisms (C481T, A803G, G857A and G590A) by PCR-RFLP methods." (PMID 30090210, 2018). "The results of previous studies that evaluated the NAT2 polymorphisms with the risk of endometriosis are controversial." (PMID 30090210, 2018). "Our results revealed that there was significant difference in the genotype distributions and allele frequencies of NAT2 G590A polymorphism between the women with endometriosis and control groups." (PMID 30090210, 2018). "In this study, the association of NAT2 polymorphisms with susceptibility to endometriosis was evaluated in an Iranian population." (PMID 30090210, 2018). "Some researchers have speculated that changes in NAT2 activity increase the risk of endometriosis or that there is a link between an imbalance in NAT2 gene polymorphisms and susceptibility to endometriosis." (PMID 31881062, 2019). "However, despite these limitations, based on an elaborately designed protocol and using comprehensive methods to evaluate previous studies, we conclude that there is an association between NAT2 polymorphisms and endometriosis." (PMID 31881062, 2019).
endometriosis (continued). "Accordingly, in this study, a meta-analysis was performed to clarify whether different NAT2 phenotypes or the SNPs rs1799929, rs1799930, rs1208, and rs1799931 are associated with susceptibility to endometriosis worldwide." (PMID 31881062, 2019). "In addition, a subgroup analysis of NAT2 phenotypes and endometriosis risk based on ethnicity was performed." (PMID 31881062, 2019). "There was substantial heterogeneity among results with respect to the association between the NAT2 phenotype and endometriosis risk, and these differences might be related to race and geographical differences." (PMID 31881062, 2019). "The NAT2 G590A SNP may be associated with susceptibility to endometriosis and the 590A allele may have a protective role in development of endometriosis." (PMID 30090210, 2018). "Specifically, it was found a significant difference in the genotype distributions and allele frequencies of NAT2 G590A polymorphisms between patients with endometriosis and healthy women; in particular, a protective role for NAT2 590A allele in the progression of endometriosis was reported." (PMID 30555665, 2018). "Their results suggest that altered NAT2 enzyme activity may be a predisposition factor in endometriosis." (PMID 30090210, 2018). "In fact, we think that the polymorphisms of NAT2 gene and the subsequent translated enzymes may differently contribute in these three different types of endometriosis that are known to have distinguished pathogenesis." (PMID 30555665, 2018). "Therefore, in the current study, it was decided to investigate the association of NAT2 C481T (rs1799929), G590A (rs1799930), A803G (rs1208) and G857A (rs1799931) polymorphisms with endometriosis in an Iranian population." (PMID 30090210, 2018). "The NAT2 481C, 803A, 590A, 587A haplotype was associated with a higher risk of endometriosis." (PMID 30090210, 2018). "However, the role of NAT2 polymorphisms in endometriosis remains to be discovered." (PMID 31881062, 2019). "Investigation of NAT2 polymorphisms (C481T, A803-G, G857A and G590A) showed that there may be an association between G590A polymorphism and risk for development of endometriosis in Iranian population, and the 590A allele may have a protective role in development of endometriosis." (PMID 30090210, 2018). "These SNPs and NAT2 phenotype are potential biomarkers for the diagnosis and treatment of endometriosis." (PMID 31881062, 2019). "Despite many studies on the role of N-acetyltransferase 2 (NAT2) in endometriosis, its clinical significance is unclear." (PMID 31881062, 2019). "Accordingly, NAT2 phenotypes and SNPs are potential biomarkers for the diagnosis and treatment of endometriosis." (PMID 31881062, 2019). "These authors evaluated the association between some polymorphisms of human arylamine N-acetyltransferase 2 (NAT2) gene (in particular C481T, A803G, G857A and G590A) and the risk of endometriosis development." (PMID 30555665, 2018). "The NAT2 *4/*6 genotype was significantly more common among endometriosis patients (35.2%) than the controls (8.1%) or unaffected women (4.2%)." (PMID 30090210, 2018). "Here, we further analyzed the relationship among NAT2 phenotypes, genotypes, and endometriosis." (PMID 31881062, 2019). "This study comprised a meta-analysis of the NAT2 slow acetylation phenotype and endometriosis." (PMID 31881062, 2019). "However, no statistically significant results were found between the NAT2 slow acetylation phenotype and endometriosis risk in Caucasians." (PMID 31881062, 2019). "Thus, there is no consensus regarding whether the NAT2 gene is associated with endometriosis." (PMID 31881062, 2019).
injury (5 papers, 2020 to 2025). Damage inflicted on the body as the direct or indirect result of an external force, with or without disruption of structural continuity. "Specific types of NAT2 alleles are known to be correlated with distinct metabolic activities; patients with a NAT2 that is inactive against isoniazid have been reported to have a higher risk of developing antituberculosis-drug-induced liver injury." (PMID 33706752, 2021). "Until now, only one study reported the miRNA targeting NAT2 gene, in which miR-217 was observed to suppress proliferation and promote apoptosis by binding to NAT2 transcript in the liver cells from rat model with CCl4-induced liver injury." (PMID 34888351, 2021). "A noteworthy study concluded that microRNA-217–targeting NAT2 restrains proliferation and promotes apoptosis and autophagy in rat models of CCL4-induced liver injury." (PMID 34867333, 2021). "In summary, our results identified hsa-miR-15a-3p as a novel epigenetic factor modulating NAT2 expression and as a protective module against INH-induced liver injury, and provided new clues to elucidate the epigenetic regulatory mechanisms concerning drug-induced liver injury (DILI)." (PMID 34888351, 2021).
adenoma (4 papers, 2012 to 2025). A neoplasm arising from the epithelium. "Two case-control studies have suggested that the combination of high CYP1A2 and high NAT2 activity is a risk factor for CRC or adenoma in individuals exposed to HAAs through the regular consumption of well-done meat." (PMID 34099058, 2021). "Similarly, heterocyclic amines in well-done beef induce CYP1A2, a mechanism implicated in adenoma risk; individuals with high N-acetyltransferase-2 (NAT2) activity and high heterocyclic amine intake show increased risk compared with lower-intake groups." (PMID 41158125, 2025). "A number of studies have suggested a stronger association between CRC or its precursor, adenoma, and red meat consumption among individuals with the rapid NAT2 phenotype, although not consistently." (PMID 26683305, 2015).